WT1 (WT1 transcription factor)
Diseases named in the same sentence as WT1 in open-access papers (continued):
Sharing a sentence is not in itself a finding about the gene and the disease.
prostate carcinoma (continued). "Thus, in prostate cancer WT1 may function as a novel oncogene facilitating development of the lethal metastatic phenotype." (PMID 23298185, 2013). "Thus, these genes could be part of a novel network of regulatory pathways initiated by WT1 and have important implications in the progression of prostate cancer." (PMID 18631392, 2008). "The tumor suppressor features of miRNA-642 was also confirmed by an alteration of expression of potential target genes, such as WT1, NUAK1, RASSF3, SKP2, GPS2 and IGFBP3, in prostate cancer." (PMID 37108073, 2023). "miRNA-642a-5p acts as a tumor suppressor by targeting Wilms Tumor 1 (WT1) gene and cell-cycle progression in prostate cancer." (PMID 35457012, 2022). "Studies have found that pro-apoptotic WT1 regulator (PAWR) conducted cell apoptosis, which inhibited the growth of prostate cancer cells." (PMID 34679847, 2021). "TP73 and WT1, which were also misregulated upon PLAGL1 knockdown, were previously found to be highly methylated in prostate cancer, along with PLAGL1." (PMID 33171905, 2020). "Evolutionary conserved WT1 and SP1 sites in the PSA promoter were confirmed by ChIP to bind both WT1 and SP1 in LNCaP prostate cancer cells chromatin." (PMID 18631392, 2008). "Evolutionary conserved transcription factor binding sites (TFBS) recognized by WT1, EGR1, SP1, SP2, AP2 and GATA1 were identified in the promoters of 24 differentially expressed prostate cancer genes from eight mammalian species." (PMID 18631392, 2008). "Two genes that regulate prostate cancer progression by enhancing growth and blood supply, AR and VEGF, have multiple WT1 and SP1 binding sites in their proximal promoter regions." (PMID 18631392, 2008). "In the same way, we observed that the corresponding mRNAs – FGFR1, TACC1, and WT1 on the one hand, and MART1 on the other hand – are overexpressed in HR and HS stage LuCaP 23.1 prostate carcinoma, respectively." (PMID 17137506, 2006). "This may be due to different chromatin states between DSRCT and prostate cancer cells, or could suggest a model in which AR binds to EWSR1::WT1, resulting in AR recruitment to WT1 binding sites." (PMID 38575753, 2024). "In previous studies, transcription factor WT1 was shown to regulate AOC1 expression; however, its association with AOC1 in prostate cancer is not strong." (PMID 35922412, 2022). "Although WT1 repressed expression of E-cadherin, a gene that must be suppressed prior to cancer cell migration and is lost during EMT, it is not clear to what extent WT1 contributes to EMT or metastasis of prostate cancer cells." (PMID 23298185, 2013). "In three of four established prostate cancer cell lines, WT1 expression was also significantly higher than the non-neoplastic cell line RWPE-1." (PMID 20426842, 2010). "Both WT1 and EGR1 have been identified in prostate cancer cells, although their function in prostate epithelium is unknown." (PMID 18631392, 2008). "We found that expression of FGFR1, WT1, and, to a lesser extent, TACC1 protein is upregulated in advanced stages (pT3 and/or N1/M1) of prostate cancer, whereas MART1 is mainly expressed in localized (pT2) stage prostate cancer." (PMID 17137506, 2006). "We have also found that FGFR1 and WT1 mRNA are preferentially expressed in pT3 and/or N1/M1 carcinoma samples, and that MART1 expression is correlated with HS stage LuCaP 23.1 carcinoma and pT2 prostate carcinoma." (PMID 17137506, 2006).
aniridia (35 papers, 2007 to 2025). Aniridia is a congenital ocular malformation characterized by the complete or partial absence of the iris. "A gene that causes aniridia (PAX-6) is located near the WT1 gene on Chromosome 11p13 and deletions encompassing the WT1 and aniridia genes explain the association between aniridia and WT." (PMID 19718304, 2007). "Contiguous gene deletions of PAX6 and neighboring genes, such as WT1, are involved in a syndromic form of aniridia characterized by Wilms tumor, Aniridia, Genitourinary anomalies, and mental Retardation called WAGR syndrome." (PMID 37269011, 2023). "Up to one-third of sporadic cases of aniridia are associated with PAX6 and WT1 deletions, while the remaining two-thirds are considered to be most likely caused by de novo point mutations." (PMID 31861090, 2019). "Some sporadic cases have a risk of developing Wilms tumor as a part of WAGR (Wilms tumor, aniridia, genitourinary abnormalities, and mental retardation; OMIM 194072), which is caused by deletion of both PAX6 and Wilms’ tumor gene (WT1) in the 11p13 region." (PMID 22393275, 2012). "Therefore, one of the primary goals of genetic evaluation in patients with aniridia is to exclude PAX6 deletions that extend to the WT1 gene." (PMID 37542296, 2023). "About 40–60% of patients with deletions encompassing both the PAX6 and WT1 genes develop WAGR syndrome (characterized by Wilms’ tumor, Aniridia, and Genitourinary abnormalities as well as mental Retardation) (OMIM #194072)." (PMID 32708836, 2020). "Large deletions that encompass PAX6 and other neighbour genes, such as WT1, result in systemic disease, such as WAGR, caracterised by the presence of Wilms tumour, aniridia, genitourinary anomalies, and retardation characterize (described in Section 6.2)." (PMID 31861090, 2019).
glioblastoma (35 papers, 2012 to 2025). The most malignant astrocytic tumor (WHO grade IV). "Wilms tumor 1 (WT1) was previously identified as a tumor-associated antigen (TAA) in high-grade glioblastoma." (PMID 36011015, 2022). "In glioblastomas, WT1 significantly associates the poor prognostic variables including old age, IDH1 negativity, and high Bcl2 and Ki67 labelling indices." (PMID 32856872, 2020). "On the contrary, other investigators observed higher WT1 scores in the IDH-positive glioblastomas that didn’t reach significant statistical associations." (PMID 32856872, 2020). "In glioblastomas, WT1 significantly associated poor prognostic variables: older age, negative-IDH1 status, high Bcl2 and Ki67 labelling indices (p=0.04, <0.001, =0.001 and <0.001 respectively)." (PMID 32856872, 2020). "Differently, WT1 silencing in glioblastoma causes decreased viability by IFG-1R overexpression, which causes a non-apoptotic, non-autophagic programmed cell death termed “paraptosis”." (PMID 25474318, 2014). "In glioblastoma, Wilms tumor 1 (WT1) is recognized as a tumor-associated antigen (TAA)." (PMID 38932383, 2024). "SDC4 has been associated with the outcome of a WT1 immuno therapy in glioblastomas." (PMID 32604718, 2020). "In this phase I, open-label, dose-escalation and expansion two-part study, the WT2725 dosing emulsion was administered as a monotherapy to patients with advanced malignancies known to overexpress WT1, including glioblastoma." (PMID 34785698, 2021). "A large number of CD4+ T cells, CD8+ T cells, and NK cells including WT1-specific CD8+ and CD4+ T cells infiltrated into the glioblastoma in WT1 peptide vaccine-treated mice." (PMID 34355173, 2021). "Wilms’ tumor gene 1 (WT1) peptide vaccine and anti-programmed cell death-1 (anti-PD-1) antibody are expected as immunotherapies to improve the clinical outcome of glioblastoma." (PMID 34355173, 2021). "Mice were transplanted with WT1 and programmed cell death-ligand 1 doubly expressing glioblastoma cells into brain followed by treatment with WT1 peptide vaccine, anti-PD-1 antibody, or the combination of the two, and survival of each therapy was compared." (PMID 34355173, 2021). "In a non-randomized trial, another peptide vaccine against WT1 improved the survival of patients with glioblastoma by stimulating the anti- WT1 IgG responses." (PMID 34675919, 2021). "Glioblastomas, gliosarcomas and subependymal giant cell astrocytomas were the most frequently WT1 expressing tumors with frequent +3 WT1 score." (PMID 32856872, 2020). "In glioblastoma, WT1 functions as an oncogene by maintaining high proliferative rate and inhibiting apoptosis." (PMID 32856872, 2020). "All gliosarcomas, 75% of SEGAs and 57.9% of glioblastomas were WT1 score+3, then 26.3% of glioblastomas and 25% of SEGAs were of WT1 score+2." (PMID 32856872, 2020). "Commensurate with this perspective, two groups in Japan have developed an anti-WT1 peptide vaccine aimed at reducing WT1 protein activity in glioblastoma multiforme patients that is currently undergoing phase II clinical trial." (PMID 29623275, 2018). "WT1 overexpression was observed in 98% of glioblastoma primary cell samples and 83% of anaplastic astrocytomas compared to 53% of grade II oligodendroglioma and pilocytic astrocytomas." (PMID 29623275, 2018). "In this study, we identified SDC-4 as a biomarker to predict clinical outcome using peripheral blood mononuclear cells obtained from patients with glioblastoma, a malignant brain tumor, who were treated with WT1 peptide vaccine." (PMID 28116121, 2016). "Thirty-two candidate genes that differentially expressed between long- and short-term survivors in peripheral blood mononuclear cells prior to WT1 peptide vaccination in 30 glioblastoma multiforme patients in a discovery set." (PMID 28116121, 2016).
glioblastoma (continued). "In this study, among patients with glioblastoma who received WT1 peptide vaccine, low SDC-4 expression level in PBMCs prior to vaccination was a prognostic factor for long-term survivors." (PMID 28116121, 2016). "Our preliminary tumor response and biological marker data suggest that WT2725 dosing emulsion may exert antitumor activity in malignancies known to overexpress the WT1 protein, particularly glioblastoma, and provide a rationale for future clinical development." (PMID 34785698, 2021). "Preliminary tumor response and biological marker data suggest that WT2725 dosing emulsion may exert antitumor activity in malignancies known to overexpress the WT1 protein, particularly glioblastoma, and provide a rationale for future clinical development." (PMID 34785698, 2021). "WT1 peptide vaccine therapy have shown favorable clinical effects against glioblastoma." (PMID 34355173, 2021). "Furthermore, WT1 peptide vaccine therapy induced strong infiltration of both innate and adaptive immune cells into glioblastoma, resulting in the conversion of the “cold” tumors into “hot” ones." (PMID 34355173, 2021). "For example, in the study of glioblastoma, WT1 may affect the viability and chemoresistance of glioblastoma cells in vitro by regulating the expression of the insulin-like growth factor 1 receptor (IGF1-R) Pathway." (PMID 34692659, 2021). "Different therapies of WT1 peptide vaccine and anti-PD-1 antibody could be simultaneously performed and both therapies showed clinical efficacy in our mouse glioblastoma model." (PMID 34355173, 2021). "In grade IV tumors, WT1 score was significantly higher in older age patients, a finding that has been confirmed previously, providing a link between WT1 expression and poor prognosis in glioblastomas and gliosarcomas." (PMID 32856872, 2020). "Furthermore, WT1 functions as a survival and undifferentiation factor in glioblastoma, as WT1 gene silencing decreases the viability and chemoresistance of glioblastoma cells in vitro." (PMID 32856872, 2020). "Excitingly, WT1 and CHTOP share binding affinity for the same promoter sequence, implicating WT1 as a strong contender for influencing sustained pathogenic transcriptional signaling in glioblastoma." (PMID 29623275, 2018). "In glioblastoma multiforme, WT1 over-expression may facilitate competition or co-operative binding with other transcription factors capable of recognizing 5hmC occupancy at promoter and enhancer sequences." (PMID 29623275, 2018). "Considering the high mortality rate of this tumor and an immediate need for an efficient strategy for its therapy, elucidating potential roles of WT1 and its potential interaction with TETs/oxi-mCs in glioblastomas should represent an important direction for future research." (PMID 29623275, 2018). "Our results clearly demonstrated that WT1 peptide vaccine and anti-PD-1 antibody therapies worked in the different steps of cancer-immunity cycle and that the combination of the two therapies could work synergistically against glioblastoma." (PMID 34355173, 2021). "Furthermore, it was reported the expression of CD97 was consistently suppressed in glioblastoma cell lines along with the silencing of WT1, which suggested the possible upregulation of CD97 and its invasiveness promotion role were mediated by the regulation or expressional changes of other genes." (PMID 22768192, 2012). "A WT1 protein-derived peptide vaccine (DSP-7888) has completed a phase I clinical trial in a variety of advanced malignancies, including recurrent glioblastomas." (PMID 37568717, 2023). "These cohorts were restricted to patients with glioblastoma and AML, in order to accumulate more data in these types of malignancy, which typically have relatively high frequencies of WT1 expression." (PMID 34785698, 2021). "The phase I trial showed promising tolerability in advanced malignancies overexpressing WT1, such as glioblastoma, with no dose-limiting toxicities reported." (PMID 40514725, 2025).
glioblastoma (continued). "Apart from the WT1-positive luminal endothelial layer, vascular proliferations of glioblastomas and pilocytic astrocytomas were WT1 negative." (PMID 32856872, 2020). "In addition, while functionally absent in normal brain tissue, WT1 levels are highly elevated in patients with glioblastoma multiforme (GBM), making it a promising immunotherapeutic target." (PMID 36138335, 2023). "Interestingly, although WT1 is not expressed in astrocytes and is found only in brain endothelium in healthy adult humans, its elevated expression is common for brain tumors such as pilocytic astrocytoma (grade I), anaplastic astrocytoma (grade III), and glioblastoma multiforme (grade IV)." (PMID 29623275, 2018).
glomerulosclerosis (34 papers, 2006 to 2025). A hardening of the kidney glomerulus caused by scarring of the blood vessels. "Experimental studies have shown that WT1 knockout in adult mouse podocytes results in proteinuria, foot process loss, and glomerulosclerosis." (PMID 37576146, 2023). "The causative role of reduced renal WT1 in podocyte dysfunction and glomerulosclerosis is well recognized." (PMID 37795410, 2023). "WT1 deletion mutations have been linked to glomerulosclerosis through the Notch and Wnt signaling pathways." (PMID 35211794, 2022). "We have found evidence for Jagged1 expression in CAGG-CreERTM+/−;Wt1f/f transgenic mice and in human biopsies of WT1-mutated glomerulosclerosis." (PMID 29398135, 2018). "In summary, we identify podocyte apoptosis as an early event in the pathogenesis of glomerulosclerosis mediated by loss of Wt1 function in mature podocytes." (PMID 29398135, 2018). "Here, we used a tamoxifen-based CRE-LoxP system to induce deletion of Wt1 in adult mice to investigate the mechanisms underlying evolution of glomerulosclerosis." (PMID 29398135, 2018). "Our study also demonstrated that loss of Wt1 in mature podocytes is associated with a reduction of FoxC2 expression and upregulation of Notch pathway components coincident with onset of glomerulosclerosis and albuminuria." (PMID 29398135, 2018). "Together, these studies suggest that loss of Wt1 in mature podocytes is associated with podocyte apoptosis and development of glomerulosclerosis." (PMID 29398135, 2018). "WT1 mutations have also been found in patients with nephrotic syndrome and isolated cases of glomerulosclerosis." (PMID 22693670, 2012). "WT1 continues to be expressed in the mature podocytes, and deletion of WT1 in mature podocytes by a tamoxifen-inducible system led to podocyte loss, increased Notch signaling and glomerulosclerosis." (PMID 31690016, 2019). "Even though children and adult mice with Wt1 mutations characteristic of Denys-Drash and Frasier syndrome develop glomerulosclerosis, it was always possible that the damage had its origin in utero, rather than reflecting a continued function for Wt1 in the maintenance of the adult kidney." (PMID 22216009, 2011). "Genetic ablation of SHROOM3 in podocytes exacerbated ADR-induced proteinuria, diminished podocyte markers (nephrin, podocin, and WT1), and accelerated glomerulosclerosis." (PMID 40558522, 2025). "While in human pathology genetic inactivation of WT1 leads to podocyte apoptosis and glomerulosclerosis, little is known how WT1 is deregulated in acquired glomerular diseases." (PMID 34323419, 2021). "In mice with WT1 knockout in podocytes, the podocyte foot processes disappeared and, consequently, glomerulosclerosis and proteinuria developed in mice." (PMID 33942367, 2021). "Animal model studies have demonstrated the relationship between reduction in WT1-labeled podocytes and glomerulosclerosis." (PMID 33147279, 2020). "Based on this study, disease onset begins at four days following initiation of WT1 deletion, and by day six extensive glomerulosclerosis occurs." (PMID 31690016, 2019). "Wt1 deletion in mature podocytes results in glomerulosclerosis with compromised renal function by day 7 post tamoxifen induction in adult CAGG-CreERTM+/−;Wt1f/f transgenic mice." (PMID 29398135, 2018). "Together, these data suggest that Notch signaling is activated when glomerulosclerosis first manifests following deletion of Wt1 in mature podocytes." (PMID 29398135, 2018). "In a model where Wt1 was deleted in mature podocytes, using a tamoxifen-based CRE-LoxP system, we observed increased podocyte loss during the development of glomerulosclerosis." (PMID 29398135, 2018). "Wt1 is essential for podocyte function as shown by the development of glomerular sclerosis in mice heterozygous for the conventional knockout and Wt1+/R394W alleles." (PMID 26035382, 2015). "We propose that glomerulosclerosis arises in part through down regulation of nephrin, a known Wt1 target gene." (PMID 22216009, 2011).
glomerulosclerosis (continued). "Moreover, decreased expression of WT1 can result in lower levels of nephrin and PODXL, which are linked to kidney diseases like glomerulosclerosis." (PMID 39844078, 2025). "Mice receiving Ccl5-deficient BM exhibited reduced albuminuria, less glomerulosclerosis, and higher WT-1+ podocyte counts, regardless of host genotype, suggesting that BM-derived CCL5 drives injury." (PMID 40986444, 2025). "Our case series emphasizes that a diagnosis of WT1 mutation can be considered in children with aHUS with severe renal manifestations without a response to C5 inhibitors and with global glomerulosclerosis on renal biopsy." (PMID 39445256, 2024). "Mechanisms underlying the development of WT1-related glomerulosclerosis are poorly understood with no effective treatments available." (PMID 29398135, 2018). "To investigate events leading to the induction of disease in these mice, we first determined the earliest point at which we could detect glomerulosclerosis after Wt1 deletion." (PMID 29398135, 2018). "Against this background we speculate that the more severe glomerulosclerosis seen in UNX males might partly be caused by the more severe lack of wt-1 and nephrin in these animals." (PMID 37624430, 2023). "Thus, loss of Wt1 in mature podocytes modulates podocyte Notch activation, which could mediate early events in WT1-related glomerulosclerosis." (PMID 29398135, 2018). "Furthermore, the re-expression of Pax-2 in conjunction with WT1 in human podocytes may serve as a forerunner to a recapitulation of developmental paradigms leading to podocyte de-differentiation in glomerulosclerosis." (PMID 23029522, 2012). "In animal models, disruption of WT1 can lead to an early GBM thickening and, finally, glomerular sclerosis." (PMID 38791159, 2024). "Similarly, although glomerulosclerosis and interstitial fibrosis were not different in ARB and TRX groups, a more detailed analysis showed the superior maintenance of WT-1 positive cells, a marker of differentiated podocytes, with ARB treatment." (PMID 35682697, 2022).